LEP (leptin)
Diseases named in the same sentence as LEP in open-access papers (continued):
Sharing a sentence is not in itself a finding about the gene and the disease.
ovarian cancer (continued). "Moreover, to elucidate the molecular mechanisms of leptin in ovarian cancer cells, changes in the expression levels of 80 cytokines were evaluated after leptin treatment." (PMID 37155466, 2023). "Leptin is a kind of adipocyte‐secreted hormone and plays different roles in ovarian cancer." (PMID 37605299, 2023). "Similarly, Ptak, Kolaczkowska & Gregoraszczuk (2013) examined the effects of leptin on the proliferation of OVCAR-3 ovarian cancer cells in a dose-dependent manner and showed that leptin (2 ng/ml–100 ng/ml) increased the proliferation of cells." (PMID 37155466, 2023). "Survival database analysis of 1656 ovarian cancer patients identified those with high leptin (n = 108) and low leptin (n = 112) and showed that median leptin expression is associated with poorer prognosis in patients previously treated with platinum and paclitaxel/docetaxel." (PMID 35565396, 2022). "In patients who had undergone paclitaxel chemotherapy, high leptin expression was associated with activation of EMT gene enrichment, suggesting high leptin expression may lead to paclitaxel resistance through activation of EMT in ovarian cancer." (PMID 36230617, 2022). "Interestingly, Leptin is one of the six-marker panel identified that can predict early-stage ovarian cancer, suggesting a possible role of Leptin in ovarian cancer initiation." (PMID 35565396, 2022). "Leptin was demonstrated to increase ovarian cancer growth in a dose-dependent manner in vitro." (PMID 36230617, 2022). "In addition to having an important role in the regulation of food intake and body mass, Leptin has been shown to directly contribute to chemoresistance in ovarian cancer cells." (PMID 35565396, 2022). "Furthermore, leptin showed an anti-apoptotic effect on ovarian cancer cells in vitro by inhibiting poly (ADP-ribose) polymerase (PARP) cleavage." (PMID 36230617, 2022). "Leptin was noted to reduce the proportion of cells in the G2/M phase in HO8910PM and OV-MZ-15 ovarian cancer lines cells treated with paclitaxel, suggesting that leptin may reduce the sensitivity of ovarian cancer cells to paclitaxel’s effect on microtubules." (PMID 36230617, 2022). "Treatment with recombinant leptin was found to contribute to ovarian cancer cell migration, invasion, peritoneal metastasis and epithelial-mesenchymal transition (EMT), and the malignant phenotypes were caused by activation of the PI3K/Akt/mTOR signaling pathway." (PMID 33799880, 2021). "Our results align with the decreased plasma levels of leptin in ovarian cancer patients." (PMID 34530759, 2021). "In addition, leptin was found to elicit matrix metalloproteinase 7 expression, leading to increased ovarian cancer cell invasion via ERK and JNK pathway activation." (PMID 33799880, 2021). "The inflammatory response is also inversely related to leptin levels that, together with IL-6, may be a useful prognostic marker of disease outcome as demonstrated by us in a population of advanced ovarian cancer." (PMID 33809200, 2021). "Furthermore, the RhoA-ROCK signaling axis was verified to mediate leptin-promoted uPA expression to promote cell invasion in ovarian cancer cells." (PMID 33799880, 2021). "The influence of leptin on chemoresistance in epithelial ovarian cancer has been studied." (PMID 33799880, 2021). "Other authors showed that women affected by ovarian cancer with a low leptin/adiponectin ratio had statistically longer progression-free survival times (using Kaplan–Meier survival estimates) than those with a higher leptin/adiponectin ratio." (PMID 31212761, 2019). "Furthermore, these investigators recorded that leptin contributed to the maintenance of stemness (i.e., stem cell characteristics) and the mesenchymal phenotype in ovarian cancer cells." (PMID 30510663, 2018). "The leptin-mediated OVCAR-3 ovarian cancer migration and MMP9 expression could be blocked by 17β-estradiol treatment." (PMID 29682217, 2018).
ovarian cancer (continued). "Generally, reduced serum leptin levels have been observed in ovarian cancer patients." (PMID 30510663, 2018). "However, overexpression of leptin and Ob-R in ovarian cancer tissue has indicated aggressive disease." (PMID 30510663, 2018). "In addition to the impact of the axis, leptin level alone displayed the positive correlation with poor outcome in ovarian cancer, and higher leptin level was found in multiple myeloma patients and associated with clinical stage." (PMID 29682217, 2018). "Likewise, in another study, the plasma level of leptin was decreased in patients with ovarian cancer (n=151) compared to healthy controls (n=75)." (PMID 30510663, 2018). "In summary, our findings suggest that the OB3 peptide may prevent leptin-induced ovarian cancer initiation and progression by disrupting leptin-induced proliferative signals via STAT3 phosphorylation and ERα activation." (PMID 28750624, 2017). "On the other hand, leptin induced cell proliferation in ovarian cancer cells which could be inhibited by co-incubation with OB3." (PMID 28750624, 2017). "Leptin and its receptor (OB-R) were shown to stimulate the proliferation of ovarian cancer cells." (PMID 28750624, 2017). "This study collectively suggests that leptin/LEPR signaling via JAK2/STAT3 has the potential to significantly impact on pathogenesis in a subset of ovarian cancer patients who may benefit from strategies that dampen this pathway." (PMID 29212170, 2017). "Evidence showed that leptin may play a role in the development of ovarian cancers; however, its prognostic value is still undetermined, and the molecular basis of these effects also remains unclear." (PMID 28750624, 2017). "Furthermore, the proliferative effect of leptin in ovarian cancer cells was inhibited by ICI 182,780." (PMID 28750624, 2017). "Leptin and OB-R were demonstrated to stimulate the proliferation of ovarian cancer cells." (PMID 28750624, 2017). "As described by us, higher ObR expression and a leptin-stimulatory effect on its own receptor in cancer granulosa cells correspond with our previously published data in epithelial ovarian cancer cells, suggesting similar effects in both epithelial ovarian cancer and folliculoma." (PMID 28861689, 2017). "Importantly, amongst women with epithelial ovarian cancer, there was a significant correlation between BMI and leptin levels, with patients with a low leptin:adiponectin ratio demonstrating statistically longer disease-specific survival." (PMID 29212170, 2017). "Little is known regarding leptin's effects on ovarian cancer cells." (PMID 26053184, 2015). "Based on these facts, we postulated that the leptin/OB-Rb pathway could contribute to ovarian cancer recurrence and progression, particularly in obese women, resulting in a worse survival rate." (PMID 26053184, 2015). "It was previously shown that leptin induces cell growth in ovarian cancer cells." (PMID 26053184, 2015). "Taken together, our results demonstrate that leptin mediates the aggressiveness of epithelial cancer and offer an explanation as to why ovarian cancer patients with higher circulating serum leptin levels or leptin receptor-expressing tumors experience a worse survival rate." (PMID 26053184, 2015). "A concept similar to ours was applied in ovarian cancer, with results showing that a combination of four serologic markers (leptin, prolactin, osteopontin, and insulin-like growth factor-II) had greater sensitivity and specificity for ovarian cancer than any of these markers alone." (PMID 25188229, 2014). "In summary, we found that a 6‐month home‐based exercise intervention in women with ovarian cancer resulted in a reduction in leptin and IGF‐1 levels which may have a beneficial effect on cancer‐related outcomes, but also an increase in circulating levels of VEGF." (PMID 37269192, 2023).
ovarian cancer (continued). "Furthermore, the same authors demonstrated how leptin may be involved in the maintenance of stemness and may display a mesenchymal phenotype in ovarian cancer cells, thus contributing to tumor progression." (PMID 37509120, 2023). "Therefore, in ovarian cancer, the effect of estrogen and leptin on tumor is more complex." (PMID 34485124, 2021). "These consequences may affect the growth of ovarian cancer or other leptin-related cancers." (PMID 28750624, 2017). "Thus, it is possible to hypothesize that leptin would act as a cell movement stimulus for ovarian cancer cells, as described for other cytokine family members, growth factors and extracellular matrix components." (PMID 26053184, 2015). "Indeed higher levels of leptin in ovarian cancer patients correlate with worse clinical outcome." (PMID 27382614, 2014). "However, circulating leptin is an essential factor regulating fat metabolism, it can be hypothesized that leptin itself might be involved in the development of ovarian cancer." (PMID 19765303, 2009). "Mesenteric fat secretes adipokines and cytokines such as leptin, adiponectin, TNF-α, and IL-6, creating a pro-inflammatory environment that drives ovarian cancer cell proliferation and migration." (PMID 39285292, 2024). "In this study, the effects of increasing the concentration of leptin were investigated on the cell viability of OVCAR-3 and MDAH-2774 ovarian cancer lines by MTT assay." (PMID 37155466, 2023). "In 2017, Fiedor and collaborators identified super-active human leptin antagonists (SHLA, D23L/L39A/D40A/F41A mutant), triple Lan1, and quadruple Lan2 leptin mutein as promising treatments for ovarian cancer, particularly the folliculoma type." (PMID 37509120, 2023). "In this study, the effects of increasing concentration of leptin were investigated on cell viability of OVCAR-3 and MDAH-2774 ovarian cancer lines." (PMID 37155466, 2023). "In this study, the effects of leptin were investigated on the viability of human OVCAR-3 and MDAH-2774 ovarian cancer cell lines with different genotypes." (PMID 37155466, 2023). "For this purpose, changes in cytokines secreted from leptin-treated OVCAR-3 and MDAH-2774 ovarian cancer cells were investigated by a human cytokine antibody array." (PMID 37155466, 2023). "The study showed that leptin stimulation led to an increased proliferation, survival and migration of LEPR-expressing ovarian cancer cell lines, with these effects shown to be mediated by the JAK2/ STAT3 pathway." (PMID 37238197, 2023). "Leptin increases MMP-7 expression and subsequent migration and invasion of ovarian cancer cell lines via ObRb, ERK1/2 and JNK1/2 activation signaling pathways and ObRb gene silencing suppresses leptin-induced MMP-7 expression." (PMID 37686525, 2023). "Ovarian cancer patients were treated with paclitaxel (PTX) chemotherapy and the leptin mRNA expression data were analysed." (PMID 36556428, 2022). "We investigate several markers of altered metabolism in ovarian cancer including hypoxia-induced factor 1, VEGF, leptin, insulin-like growth factors, and glucose transporters." (PMID 36230617, 2022). "Exogenous treatment of leptin in SKOV3 and OVCAR3 ovarian cancer cells resulted in the activation of EKR1/2 and JNK1/2 and induced expression of MMP-7, -2, and -9, which are factors known to induce migration." (PMID 35565396, 2022). "Therefore, adipocyte-secreted leptin could be a target for potential therapies of ovarian cancer." (PMID 34440886, 2021). "However, there is a strong need to conduct further research to confirm the precise function of adiponectin and leptin in ovarian cancer development or whether there is any correlation between the stage of ovarian cancer, histological type and adiponectin, leptin expression." (PMID 33809784, 2021). "On the other hand, both leptin and OB3 activated PI3K in ovarian cancer cells, which were inhibited by LY294002." (PMID 28750624, 2017).
ovarian cancer (continued). "Ovarian cancer SKOV-3 and OVCAR-3 cells were treated with different concentrations of leptin (1 ~ 100 nM) or OB3 (1 ~ 100 μM) for 4 days with re-flashed medium and peptides daily." (PMID 28750624, 2017). "Further analysis revealed that high co-expression of leptin and LEPR correlated with reduced survival in ovarian cancer patients." (PMID 29212170, 2017). "Both inhibitors were able to suppress leptin-mediated proliferation, survival and migration in LEPR-expressing ovarian cancer cells." (PMID 29212170, 2017). "This was consistent with high co-expression of LEP and LEPR correlating with poor survival of ovarian cancer patients." (PMID 29212170, 2017). "In the present study, we compared and analyzed signal transduction and mechanisms which were activated by leptin and the OB3 peptide in ovarian cancer cells." (PMID 28750624, 2017). "In this study, we investigated the proliferative effects, gene expressions and signaling pathways modulated by leptin and OB3 in human ovarian cancer cells." (PMID 28750624, 2017). "Studies were conducted on the effects of leptin and the OB3 peptide on cell proliferation in ovarian cancer cells." (PMID 28750624, 2017). "Both leptin and OB3 activate PI3K signaling which is involved in expressions of ERα-responsive genes in ovarian cancer cells." (PMID 28750624, 2017). "Leptin has been shown to activate PI3K/Akt and ERK1/2 survival pathways and stimulate the expression of anti-apoptotic protein Mcl-1 in ovarian cancer cell line OVCAR3." (PMID 26122176, 2015). "Here, we demonstrated that high leptin levels, as observed in the obese population, indeed activate the PI3K/AKT/mTOR signaling pathway in ovarian cancer cells (e.g., SKOV3 and UCI101)." (PMID 26053184, 2015). "This study was design to investigate the prevalence of leptin and Ob-R in Middle Eastern epithelial ovarian cancer (EOC) and to analyze the role of leptin and the mechanisms under its action in EOC tissue sample and cell lines." (PMID 19765303, 2009). "There are many studies investigating the possible role of leptin in ovarian cancer, but its molecular mechanisms have not been elucidated yet." (PMID 37155466, 2023). "When stratified by recurrence of ovarian cancer during the study, in the group who did not experience a recurrence, the exercise intervention effect for serum leptin was not significant (p = 0.40)." (PMID 37269192, 2023). "Similarly, in a separate study, leptin treatment was shown to induce migration and wound healing capacity in SKOV3 and HEY3 ovarian cancer cell lines." (PMID 35565396, 2022). "Besides, inhibition of established tumorigenic effects of leptin via direct inhibition of the PI3K pathway, which is activated in ovarian cancer cells, has also been demonstrated by numerous studies." (PMID 34751020, 2022). "Leptin acts on a transmembrane receptor called Ob-R/LEPR, which could be present also in ovarian cancer cells." (PMID 34440886, 2021). "OB3 peptide did not promote cell growth in ovarian cancer cells, furthermore, it inhibited leptin-induced proliferative signals when it was used in combination with leptin." (PMID 34356668, 2021). "Finally, we report that leptin has the greatest biological relevance in EMT and tumor progression in breast, lung, prostate, esophageal, and ovarian cancer." (PMID 33334030, 2020). "Also, Leptin promoted ovarian cancer proliferation by induced phosphorylation of STAT5 in SKOV3 and A2780 cells, which mediated leptin-induced expression of miR-182 and miR-96 and subsequent inhibition of Forkhead box O3." (PMID 31861720, 2019). "Apart from the similar findings like lower serum leptin concentrations in ovarian cancer patients than controls (n=51), the investigators of a study also found that patients with stage III/IV (n=38) had lower mean serum leptin levels in comparison to patients with I/II stage (n=15)." (PMID 30510663, 2018).
ovarian cancer (continued). "Leptin is also believed to influence cancer prognosis by promoting cancer cell migration and invasion through leptin mediated activation of JAK/STAT3, and by promoting focal adhesion formation, maintenance of stemness and mesenchymal phenotypes in ovarian cancer cells." (PMID 29662629, 2018). "The combination of the mentioned six biomarkers (MIF, OPN, CA125, IGF II, leptin and prolactin) has been shown to improve differentiation between disease free and ovarian cancer patients compared to CA125 alone in patients without a family history of OC." (PMID 29244844, 2017). "A role for leptin/LEPR in the survival of ovarian cancer cells was also demonstrated, similarly through the JAK2/STAT3 pathway, consistent with a previous study showing an alternate JAK2 inhibitor was able to induce apoptosis in ovarian cancer cells." (PMID 29212170, 2017). "Therefore, studies were conducted to examine the roles of ERα in leptin and OB3-induced biological activities in ovarian cancer SKOV-3 and OVCAR3 cells." (PMID 28750624, 2017). "Leptin stimulation led to increased proliferation, survival and migration of LEPR-expressing ovarian cancer cell lines, with the effects shown to be mediated by the downstream Janus kinase 2/Signal transducer and activator of transcription 3 (JAK2/STAT3) pathway." (PMID 29212170, 2017). "Furthermore, high co-expression of LEP and LEPR within the tumor clearly represented a poor prognostic factor for epithelial ovarian cancer, consistent with another recent study." (PMID 29212170, 2017). "No findings have been reported regarding leptin's effects on the migration and invasion of ovarian cancer cells or the dominant signaling pathways." (PMID 26053184, 2015). "By plotting the putative copy-number alterations (CNA) and mRNA expression levels for LEP and LEPR, we found that the upregulation or amplification of the LEP gene in ovarian cancer correlates with a slight increase in the LEP mRNA levels in the samples analyzed by RNA Seq V2 in the TCGA database." (PMID 26053184, 2015). "Approximately 20% of ovarian cancers (110 cases, 90% in stage III-IV) exhibited alterations (mRNA upregulation or amplification) in either leptin or OB-Rb levels (using an mRNA expression threshold Z-score±1 and a protein/phospho-protein expression threshold Z-score±2)." (PMID 26053184, 2015). "The effects of leptin on cytokines in ovarian cancer cells have not been investigated yet." (PMID 37155466, 2023). "However, experimental results from another research group showed that serum levels of leptin were not correlated with the response to paclitaxel/carboplatin therapy in ovarian cancer patients." (PMID 33799880, 2021). "In this review, we describe the effect of leptin on epithelial–mesenchymal transition (EMT) markers in different study models, including in vitro, in vivo, and patient studies and in various types of cancer, including breast, prostate, lung, and ovarian cancer." (PMID 33334030, 2020). "However, unlike other cancers, a lower mean level of circulating leptin has been observed commonly among patients with epithelial ovarian cancer in comparison to non-cancerous or healthy controls." (PMID 30510663, 2018). "However, the interaction between leptin signaling and PI3K/AKT pathway in ovarian cancer remains unknown." (PMID 19765303, 2009). "To summarize, we suggest that leptin may promote progression from G1 to S phase by stimulating expression of cyclin D1 and inhibiting that of p21WAF1/CIP1, as well as progression to the S phase by stimulating the expression of cyclin A in an ovarian cancer cell line." (PMID 22968658, 2013). "They found that leptin did not affect the proliferation of SKOV3 and IOSE-80PC ovarian cancer cell lines." (PMID 37155466, 2023). "We found that Leptin, but not OB3 peptide, stimulated ovarian cancer cell proliferation and gene expression." (PMID 28750624, 2017).